PRDX5 (peroxiredoxin 5)
Diseases named in the same sentence as PRDX5 in open-access papers (continued):
Sharing a sentence is not in itself a finding about the gene and the disease.
prostate carcinoma (6 papers, 2012 to 2025). A carcinoma that arises from epithelial cells of the prostate gland. "Given the notable prognostic significance of PRDX5 and its association with tumor staging and Gleason score in prostate cancer, we developed nomograms to predict patients' 3‐year and 5‐year BCR‐free survival outcomes." (PMID 40281661, 2025). "PRDX5 was a risk factor for BCR in prostate cancer patients with greater Gleason score, lymph node metastases, and higher pathological T stage (p < 0.05)." (PMID 40281661, 2025). "In conclusion, the objective of our study is to determine the value of PRDX5 as a biomarker influencing prognosis and response to treatment for prostate cancer." (PMID 40281661, 2025). "Regarding the proteomics, IHC staining analysis of prostate tissue or PCa tissue from the Human Protein Atlas database showed that higher staining of PRDX3 and PRDX5 was found in higher grade of prostate cancer." (PMID 40281661, 2025). "This indicates that the raised expression of PRDX5 in prostate cancer epithelial cells plays a pivotal role in the advancement of tumors." (PMID 40281661, 2025). "The results showed that PRDX5‐Nomo had the highest C‐index for predicting BCR for prostate cancer in CancerMap and GSE70769, ranked second in the TCGA, fifth in the DKFZ, and eighth in the GSE54460." (PMID 40281661, 2025). "The results demonstrated that PRDX5 (p = 0.038) and pathological T stage (p < 0.01) emerged as independent prognostic factors for prostate cancer." (PMID 40281661, 2025). "Previous work has demonstrated that the expression of PRDX5 in PC‐3 cells, a type of human prostate cancer, notably rises when exposed to oxidative stress." (PMID 40281661, 2025). "The expression of PRDX5 is significantly increased in prostate cancer samples (PRAD) compared to normal tissues." (PMID 38115765, 2024). "On the basis of these past studies, our research innovatively compared the prognostic impact of all six family members in prostate cancer and found that PRDX5 has the strongest predictive value for poor prognosis in PCa patients and is most closely associated with adverse outcomes." (PMID 40281661, 2025). "After determining PRDX5 as the most significant prognostic factor in the PRDX family, we developed a nomogram integrating PRDX5 expression with clinical features to better predict clinical outcomes in prostate cancer patients than 30 other 30 public gene signatures." (PMID 40281661, 2025). "Among the PRDXs family, PRDX5 was most related to the advancement of prostate cancer." (PMID 40281661, 2025). "Notably, across all 7 databases, patients in 5 datasets with high expression of PRDX5 were more likely to reach BCR, indicating that PRDX5 is the most promising biomarker within the PRDX family associated with BCR in prostate cancer." (PMID 40281661, 2025). "Our study suggests that PRDX5 inhibition could become a new concept and practice for the management of castration‐resistant prostate cancer." (PMID 38115765, 2024). "Specifically, inhibiting PRDX5 can suppress DTP cell proliferation in culture, hinder CRPC progression in animal models, and stabilize PSA progression and metastatic lesions in patients, indicating that PRDX5 could be a therapeutic target for treatment‐resistant prostate cancer." (PMID 40281661, 2025).
psoriasis (4 papers, 2022 to 2023). An autoimmune condition characterized by red, well-delineated plaques with silvery scales that are usually on the extensor surfaces and scalp. "Oxidative stress related proteins such as Peroxiredoxin-5 (P30044) and thioredoxin (P10599) were more upregulated in psoriasis with CVD risk factors than in psoriasis without CVD risk factors in the current study." (PMID 36804462, 2023). "More than 4500 cases and 10,000 controls were investigated in GWAS, where 7 non-HLA susceptibility loci shared by CD and psoriasis (9p24 near JAK2, 10q22 at ZMIZ1, 11q13 near PRDX5, 16p13 near SOCS1, 19p13 near FUT2, 17q21 at STAT3, 22q11 at YDJC) were found." (PMID 36443384, 2022).
thyroid cancer (4 papers, 2018 to 2025). "Moreover, PRDX5 has been found to play a tumor‐promoting role in thyroid cancer." (PMID 40281661, 2025).
adrenocortical carcinoma (3 papers, 2016 to 2023). "Reduced levels of Prdx5 enzymes have also been reported in adrenocortical carcinoma, indicating that several added factors and mechanisms regulate the outcome of cancer growth." (PMID 37443747, 2023). "The upregulated expression of Prdx5 is also observed in malignant mesothelioma cells, while a reduction in Prdx5 expression has only been described in adrenocortical carcinoma." (PMID 31500275, 2019). "Adrenocortical carcinoma was characterized by silencing of genes on chromosome 11q13, including PRDX5 (peroxiredoxin 5)." (PMID 27206673, 2016).
alopecia areata (3 papers, 2015 to 2022). Loss of scalp and body hair involving microscopically inflammatory patchy areas. "SNPs in the genes encoding some heat shock proteins (HSPs) and genes involved in the elimination of reactive oxygen species (ROS) such as PRDX5 and ACOX have also been linked to alopecia areata." (PMID 36292745, 2022). "A previous study showed an association of gluten antigens with the hair follicle peptide peroxiredoxin 5 (PRDX5), which is one of the genes associated with alopecia areata." (PMID 35162962, 2022). "Polymorphisms in stress-inducible protein genes such as HSPs and NKGD2 receptor ligands, as well as in genes involved in ROS clearance such as PRDX5 and ACOX, have been linked to alopecia areata." (PMID 36292745, 2022).
Arthritis (3 papers, 2019 to 2023). Inflammation of a joint. "In vivo, the effects of MaR1 treatment or Prdx5 deficiency on MSUc induced peritonitis and arthritis mouse models were evaluated." (PMID 37996809, 2023).
endometrial cancer (3 papers, 2018 to 2019). Primary or metastatic malignant neoplasm involving the endometrium (mucous membrane that lines the endometrial cavity). "Like Prdx3, the expression of Prdx5 is upregulated in endometrial cancer and this enhanced expression of Prdx5 in the endometrium of females with endometrial tumor can serve as a prognostic marker." (PMID 31500275, 2019).
Hypertension (3 papers, 2024 to 2025). The presence of chronic increased pressure in the systemic arterial system. "In particular, the decrease in Prdx5 by Ang II in DCT increased the activity of the WNK4-SPAK/OSR1-NCC axis associated with the development of hypertension." (PMID 39857434, 2025). "Next, we determined whether the deletion of Prdx5 was related to the expression and activity of NCC, which has been shown to cause hypertension, and whether the efficacy of Prdx5 was dependent on the WNK-SPAK/OSR1 pathway, the master activator of NCCs." (PMID 39857434, 2025). "Finally, it is suggested that the decrease in Prdx5 by Ang II is one of the leading causes of hypertension." (PMID 39857434, 2025). "This study aims to observe whether the deficiency of Prdx5 also contributes to the worsening of CKD-related hypertension." (PMID 39857434, 2025). "Furthermore, when stimulated with Ang II, Prdx5 deficiency is sensitive to the induction of hypertension." (PMID 39857434, 2025). "In this study, Prdx5 KO mice were used to elucidate the role of Prdx5 in Ang-II-induced hypertension." (PMID 39857434, 2025). "Since the condition with reduced Prdx5 is clinically more reliable, we re-evaluated the role of Prdx5 in Ang-II-induced hypertension using Prdx5 hetero mice." (PMID 39857434, 2025). "Prdx5 KO mice were used to observe the effect of Prdx5 deletion on Ang-II-induced hypertension." (PMID 39857434, 2025). "In this study, we aimed to elucidate whether Prdx5 plays a role in the pathogenesis of CKD-related hypertension and the molecular regulatory mechanisms by Prdx5 in the kidney." (PMID 39857434, 2025). "Taken together, Prdx5 deficiency itself is not a sufficient prerequisite for hypertension, but it is a sufficient condition for the progression of renal fibrosis." (PMID 39857434, 2025). "Therefore, we suggest that Prdx5 could be one of the prime targets for treating CKD and NCC-associated hypertension." (PMID 39857434, 2025). "For the first time, we investigated whether renal Prdx5-deletion accelerated the progression of renal fibrosis, a common feature in CKD, and whether Prdx5-deletion promoted the progression of hypertension." (PMID 39857434, 2025). "A lack of Prdx5 is responsible for the pathogenesis of CKD, hypertension." (PMID 39857434, 2025).
liver cancer (3 papers, 2021 to 2025). An epithelial or non-epithelial malignant neoplasm that arises from the liver. "Our findings suggest that PRDX5 has a protective role on β-CCE-induced liver cancer cell death and provides new insights for using its anti-cancer properties for liver cancer treatment." (PMID 36118528, 2022). "In Kaplan-Meier plotter analysis, liver cancer patients with higher PRDX5 expression had worse overall survival than those with lower PRDX5 expression." (PMID 36118528, 2022). "To explore the effects caused by the difference in PRDX5 content in liver cancer tissue on β-CCE-induced cell death, we used lentiviral vectors to over-express the PRDX5 gene in HepG2 cells." (PMID 36118528, 2022). "After performing a genetic analysis of patients with liver cancer, we found higher PRDX5 expression in the liver tissue of patients with liver cancer than in normal liver tissues." (PMID 36118528, 2022). "In this process, PRDX5 also plays an inhibitory role in regulating intracellular ROS level, which further provides an effective diagnosis and treatment mechanism for PRDX5 in the case of liver cancer." (PMID 36118528, 2022). "We over-expressed PRDX5 in HepG2 cells to explore whether a higher level of PRDX5 in liver cancer patients is related with chemotherapy resistance." (PMID 36118528, 2022). "Moreover, immunohistochemistry data for liver cancer using the Human Protein Atlas revealed that PRDX5 protein was moderately expressed in normal liver tissues but abundantly expressed in liver cancer tissues." (PMID 36118528, 2022). "High expression level of PRDX5 was deeply related with the postoperative survival of patients with liver cancer, indicating that PRDX5 may be a biomarker of live cancer processing." (PMID 36118528, 2022). "Using data from bioinformatics databases, we analysed the effect of PRDX5 expression on HCC and compared postoperative survival between different liver cancer patients and normal patients." (PMID 36118528, 2022).
Stroke (3 papers, 2017 to 2025). Sudden impairment of blood flow to a part of the brain due to occlusion or rupture of an artery to the brain. "In our study, we observed an increased PRDX2 and PRDX5 gene expression in the hemisphere affected by stroke 24 h post-induction (p < 0.0001 and p < 0.01, respectively)." (PMID 40332314, 2025). "Interestingly, studies on humans showed that the plasma concentration of PRDX5 was negatively correlated with the biomarkers of inflammation and the severity of stroke." (PMID 40332314, 2025). "During a severe stroke, peroxiredoxin 5 is consumed and its production impaired." (PMID 28988575, 2017). "For example, some findings suggest an inverse role between peroxiredoxin 5 and stroke severity." (PMID 28988575, 2017).
acute kidney injury (2 papers, 2025). Sudden and sustained deterioration of the kidney function characterized by decreased glomerular filtration rate, increased serum creatinine or oliguria. "In a recent study, a reduction or ablation of Prdx5 in the kidney was reported to be a pathophysiological phenomenon that increased the sensitivity to ischemia/reperfusion (I/R)-induced acute kidney injury and unilateral-ureteral-obstruction-induced renal fibrosis." (PMID 39857434, 2025).
brain ischemia (2 papers, 2021 to 2024). Diminished or absent blood supply to the brain caused by obstruction (thrombosis or embolism) of an artery resulting in neurologic damage. "PRDX5, involved in redox balance during brain ischemia–reperfusion, presents a dual role; intracellularly exerting neuroprotective effects and extracellularly inducing pro‐inflammatory responses." (PMID 38702954, 2024). "Human PRDX5 has been shown to enhance brain ischemia-reperfusion injury through activation of TLR2- and TLR4-mediated inflammation." (PMID 34943005, 2021). "Human peroxiredoxin-5 (PRDX5) is a unique redox-sensitive protein that plays a dual role in brain ischemia-reperfusion injury." (PMID 34943005, 2021).
Hodgkins lymphoma (2 papers, 2019 to 2023). A heterogeneous group of malignant lymphoid neoplasms of B-cell origin characterized histologically by the presence of Hodgkin and Reed-Sternberg (HRS) cells in the vast majority of cases. "Increased levels of Prdx5 have been observed in aggressive Hodgkin’s lymphomas." (PMID 31500275, 2019).
infertile (2 papers, 2024 to 2025). "Reduced PRDX5 expression has been linked to an increased susceptibility to oxidative damage and peroxide-induced apoptosis Previous proteomic studies have revealed decreased levels of PRDX5 in the spermatozoa of male patients with infertility." (PMID 39726694, 2024). "Supporting this, proteomic studies from the Cleveland Clinic demonstrated lower expression of mitochondrial antioxidant proteins (PRDX5 and SOD2) in idiopathic infertile men, suggesting mitochondrial oxidative damage as a key factor in IMI." (PMID 41011106, 2025). "PRDX5 and SOD2 were significantly underexpressed, while GSR was overexpressed in the proteomics analysis, and bioinformatics indicated a general downregulation of mitochondrial activity in the infertile group." (PMID 39726694, 2024).
multiple sclerosis (2 papers, 2015 to 2025). A progressive autoimmune disorder affecting the central nervous system resulting in demyelination. "PRDX5 (peroxiredoxin 5), a top M1 target selected in our RHI vs. CTL classification models, is an antioxidant enzyme expressed in neuronal mitochondria shown to be increased in postmortem brains of patients with multiple sclerosis and Huntington’s disease." (PMID 40524252, 2025).
osteoporosis (2 papers, 2020 to 2023). A condition of reduced bone mass, with decreased cortical thickness and a decrease in the number and size of the trabeculae of cancellous bone (but normal chemical composition), resulting in increased fracture incidence. "Genetically deficient Prdx5 male mice developed osteoporosis-like phenotypes, suggesting that Prdx5 is important in bone remodeling." (PMID 36735291, 2023).
renal fibrosis (2 papers, 2016 to 2025). A final common manifestation of a wide variety of chronic kidney diseases characterized by glomerulosclerosis and tubulointerstitial fibrosis. "In this study, we demonstrated that mitochondria forms of Prdxs (Prdx3 and Prdx5) were decreased associated with renal fibrosis in UUO rat kidneys." (PMID 26872211, 2016). "In this study, we demonstrated the association between Prdx5 expression and renal fibrosis." (PMID 26872211, 2016). "Ang-II-infused Prdx5 KO mice showed increases in blood pressure, renal injury markers, ROS, and renal fibrosis." (PMID 39857434, 2025). "In conclusion, chronic stimulation of Ang II induced a decrease in renal Prdx5, resulting in ROS/RNS production, and accelerated the progression of renal fibrosis, a hallmark of CKD." (PMID 39857434, 2025). "In the kidneys of Prdx5 KO mice, the expression of renal fibrosis markers, such as SMA, vimentin, FN, TGF-β, and CTGF, was already slightly increased compared to Prdx5 WT." (PMID 39857434, 2025). "Under Ang II infusion conditions, Prdx5 KO mice were not only vulnerable to renal damage, including increased pathological characteristics of renal fibrosis, but also showed a worsening of Ang-II-induced blood pressure elevation than Ang-II-infused WT mice." (PMID 39857434, 2025). "Among the isotypes, mitochondrial forms of Prdxs (Prdx3 and Prdx5) and Prdx6 were decreased with the progression of renal fibrosis." (PMID 26872211, 2016). "To determine involvement of Prdxs in renal fibrosis, we analyzed the expression pattern of Prdxs isotypes (Prdx1, Prdx2, Prdx3, Prdx4, Prdx5, and Prdx6) in the cortex/outer stripe of outer medulla of UUO kidney." (PMID 26872211, 2016). "Selective inhibition of Stat3 by ectopic expression of Prdx5 could be a therapeutic target in TGF-β induced renal fibrosis." (PMID 26872211, 2016). "Despite the association of Prdx5 with inflammatory regulation, the physiological effects of Prdx5 in renal fibrosis have not been fully characterized, and the underlying mechanisms remain poorly understood." (PMID 26872211, 2016). "Consequently, we suggested that Prdx5 plays a role as anti-fibrotic effector in the pathogenesis of renal fibrosis, and its regulation mechanism was through by inhibition of Stat3 activation." (PMID 26872211, 2016). "However, the physiological effects and the underlying mechanisms of Prdx5 in renal fibrosis have not been fully characterized." (PMID 26872211, 2016).
sarcopenia (2 papers, 2024 to 2025). Progressive decline in muscle mass due to aging which results in decreased functional capacity of muscles. "The combined deficiency of PRDX3 and PRDX5 accelerates muscle aging by exacerbating oxidative stress and mitochondrial dysfunction, suggesting that enhancing their activity may be a promising therapeutic strategy to prevent sarcopenia and age‐related muscle degeneration." (PMID 41147088, 2025). "Our findings provide an insight for therapy against sarcopenia through alleviating oxidative damage-induced dysfunctional mitochondria by targeting peroxiredoxin 5, which may contribute an insight for healthy aging." (PMID 38868327, 2024).
tendinopathy (2 papers, 2011 to 2017). "Also, recent studies show increased expression of peroxiredoxin 5 (PRDX5), a thioredoxin peroxidase with antioxidant properties, within tendinopathic tendons, suggesting that oxidative stress may be involved in the pathogenesis of tendinopathy." (PMID 23905032, 2011).
Autoimmunity (1 paper, 2023). The occurrence of an immune reaction against the organism's own cells or tissues. "Prdx1 and Prdx5 were the hallmark genes of macrophage cluster 1, and these genes were reported to be associated with autoimmunity." (PMID 37534129, 2023).
Cognitive impairment (1 paper, 2022). Abnormal cognition is characterized by deficits in thinking, reasoning, or remembering. "However, the upregulation in the expression of hippocampal peroxiredoxin-5, isoform CRA_a and hippocampal glutathione S-transferase Mu 1 by matcha and decaffeinated matcha might show that these enzymes could be used as markers for the evaluation of aging and cognitive impairment." (PMID 35334854, 2022).
colorectal adenocarcinoma (1 paper, 2025). The most common type of colorectal carcinoma. "There was a positive correlation between PRDX5 and GPX4 levels in colorectal adenocarcinoma patients." (PMID 40831323, 2025).
dry eye (1 paper, 2015). "Different proteins involved with dry eye dysfunction: ANXA1, ANXA11, CST4, PRDX5, PLAA and S100A6; were validated as biomarkers." (PMID 26287192, 2015).
Duchenne muscular dystrophy (1 paper, 2025). Duchenne muscular dystrophy (DMD) is a neuromuscular disease characterized by rapidly progressive muscle weakness and wasting due to degeneration of skeletal, smooth and cardiac muscle. "Prdx3 and Prdx5 levels also showed a decreasing trend in mouse models of Duchenne muscular dystrophy (DMD) and dysferlinopathy‐associated accelerated muscle degeneration." (PMID 41147088, 2025).
gastric ulcer (1 paper, 2024). An ulcerated lesion in the mucosal surface of the stomach. "Polaprezinc (POL) is a medication used to treat gastric ulcers and was reported to affect the expression of PRDX5." (PMID 38115765, 2024). "We have repurposed polaprezinc, a gastric ulcer medication, and developed stachyose, a dietary component, as a novel PRDX5 inhibitor." (PMID 38115765, 2024).